BMP4 (bone morphogenetic protein 4)
Diseases named in the same sentence as BMP4 in open-access papers (continued):
Sharing a sentence is not in itself a finding about the gene and the disease.
infection (16 papers, 2008 to 2023). The state of being infected such as from the introduction of a foreign agent such as serum, vaccine, antigenic substance or organism. "Using recombinant adenoviruses Ad-B4 and Ad-siB4, which overexpresses or silences BMP4, respectively, we infected Huh7 and HepG2 cells with high efficiency as the fluorescence signals were readily detected at 36 h after infection." (PMID 37443106, 2023). "In this study, we demonstrated that the knockout of bmp4 in zebrafish results in the increase in the viral load and mortality after infection with GCRV virus in both larvae and adults, indicating its antiviral function." (PMID 37833891, 2023). "Overexpression and silencing of BMP4 were accomplished through adenoviruses Ad-B4 and Ad-siB4 infection." (PMID 37443106, 2023). "These suggest that the expression of bmp4 is induced by infection with virus or its mimic poly(I:C)." (PMID 37833891, 2023). "The bmp4−/− mutant zebrafish significantly increases the viral load and mortality after infection with GCRV virus in both larvae and adults." (PMID 37833891, 2023). "In a comparative study of Darwin’s finches, higher and earlier expression of BMP4 was found in species with deeper, broader beaks, and this phenotype was induced in other species with smaller beaks upon infection with BMP4 retrovirus." (PMID 30717314, 2019). "When BMP2 and BMP4 were inhibited by infection with Noggin in the chicken embryo, condensation formation in the frontal bone did not progress to differentiation as detected by the absence of RUNX2 expression." (PMID 30717314, 2019). "This was possibly due to the presence of more viable cells facilitating greater second and third round infections by the virus that expresses BMP-4 and reduced capability of the parental virus to generate substantial infection of the culture at lower MOIs." (PMID 23800258, 2013). "This is potentially attributed to enhanced second and possibly third round infections facilitated by differentiation by BMP-4 action on the GBM stem cells." (PMID 23800258, 2013). "Consistent with previous findings, cultures infected with these doses of Ad.BMP-2 and Ad.BMP-4 generated approximately 30 to 60 ng/mL of gene product per 24 hours at day 3 post-infection." (PMID 19799789, 2009). "At days 8 and 14, expression of keratinocyte-specific gene was barely detected after infection with ΔNp63-lentivirus, as compared to cells cultivated in the presence of BMP-4 and serum." (PMID 18927616, 2008). "Knocking down the BMP4 expression in cultured NMCMs by infection with shBmp4 adenovirus could restore the upregulation of Parkin." (PMID 36746787, 2023). "The expression of BMP4 was detected at 72 h after infection." (PMID 37443106, 2023). "Interestingly, BMP4, a lncRNA 54128 target mRNA, was also upregulated in a virus dose-dependent manner and in an infection time-dependent manner, showing the same transcription trends as lncRNA 54128." (PMID 34452487, 2021). "We examined the expression of hallmarks of BMP signaling during mycobacterial infection and found transcript levels of Bmp2, Bmp4, Bmpr2, and Id2 were consistently upregulated upon infection of mouse peritoneal macrophages with Mtb H37Ra as well as virulent Mtb H37Rv." (PMID 29449840, 2018). "BMP-4 production could be detected in GBM CSC implants in mice brains upon GLV-1h285 infection by immunohistochemistry analysis using a BMP-4 specific antibody." (PMID 23800258, 2013). "Therefore, differentiation by BMP-4 appears to facilitate infection which can be achieved by using more virus." (PMID 23800258, 2013). "BMP4 was shown to effectively inhibit the expression of mTOCR1 signaling members, such as S6k, Deptor, Pras40, Rptor, mTor, and Srebf1 at 36h and/or 72h after Ad-B4 infection, while transiently up-regulating the expression of Lipin1 at 36h after Ad-B4 infection." (PMID 31831718, 2019).
infection (continued). "Compared with wild-type zebrafish, bmp4−/− zebrafish larvae exhibited a significantly reduced survival rate upon GCRV infection, and most of the fish died 36 h post infection, while only few wild-type zebrafish died during the period." (PMID 37833891, 2023). "The infection of NSCs with a lentivirus that contains the RFP and BMP4 sequences generated the stable NSCs-BMP4/RFP cell line." (PMID 26908439, 2016). "While, Ad-Cre infection significantly inhibited the Icariin-induced expression of BMP2, BMP4, ALP, and OC, Ad-Cre-mediated deletion of the β-catenin gene was demonstrated by the reduction of β-catenin mRNA and protein expression in these cells." (PMID 24348713, 2013). "After infection with GCRV, the survival rate of bmp4−/− zebrafish was significantly reduced." (PMID 37833891, 2023). "On day 8 after infection, the HF1 underwent morphological changes via a change from a spindle shape to a bright round shape, and cuboid-shaped cells appeared after removing CHIR99021 and BMP4 from the medium on day 14 after infection." (PMID 35883684, 2022). "Furthermore, it appears that the growth inhibition due to GLV-1h189 was by oncolytic activity alone and that of GLV-1h285 due to oncolytic activity by basic VACV infection, growth inhibition by BMP-4 protein and oncolytic activity facilitated by the differentiation carried out by the BMP-4 payload." (PMID 23800258, 2013). "Furthermore, infection of ES cells with a lentivirus expressing ΔNp63 at day 4 of differentiation did not enhance the effect of BMP-4 on keratinocyte production (data not shown)." (PMID 18927616, 2008). "Next, to functionally test whether BMP signaling regulates infection, we performed infection experiments with pseudoviruses or native SARS-CoV-2 in the absence of BMP4 and/or with the BMP inhibitor, LDN193189." (PMID 37084725, 2023).
cardiovascular disease (9 papers, 2013 to 2026). "Following its release from adipose tissue into the blood, BMP4 causes inflammation of the myocardial tissue and aorta, thus contributing to cardiovascular disease." (PMID 25678859, 2015). "Moreover, BMP-4 is a potential mediator of cardiovascular disease risk reduction after bariatric surgery." (PMID 24170999, 2013). "Among the suggested upstream regulators of AMH is BMP4, and reported downstream targets of AMH include NF-κB,which have both been linked to cardiovascular disease." (PMID 39076620, 2022). "Thus, BMP4 is expected to become a new target for the prevention and treatment of cardiovascular disease in obese patients." (PMID 25678859, 2015). "Subsequently, surplus BMP4 released into the blood could affect the vascular endothelium and the myocardium, leading to cardiovascular disease." (PMID 25678859, 2015).
metabolic disease (5 papers, 2017 to 2025). A congenital disorder (due to inherited enzyme abnormality) or acquired (due to failure of a metabolically important organ) disorder resulting from an abnormal metabolic process. "In addition, BMP4 plays a vital role in metabolic diseases and is markedly increased in patients with impaired glucose tolerance or T2DM." (PMID 37370018, 2023). "BMP4 plays an important role in the development of metabolic diseases." (PMID 35477568, 2022).
adenocarcinoma (4 papers, 2016 to 2021). A common cancer characterized by the presence of malignant glandular cells. "The results indicated that there were significant positive correlations among FSTL1, BMP4, Smad4, and p-Smad1/5/8 IHC expression in adenocarcinoma." (PMID 28852126, 2017).
hematological malignancies (3 papers, 2012 to 2025). "The frequent occurrence of BMP4 hypermethylation in various hematological malignancies makes it a promising candidate as biomarker for diagnosis, prognosis, and monitoring treatment." (PMID 41044657, 2025).
kidney disease (3 papers, 2016 to 2022). "No other family members are known to have renal disease but detailed imaging has not been carried out in all individuals who have the BMP4 variant." (PMID 30568244, 2019).
bacterial infection (2 papers, 2021). "Administration of BMP4 seems to ameliorate colon damage through an anti-inflammatory response during bacterial infection." (PMID 34692671, 2021).
colorectal (2 papers, 2011 to 2020). "Given that GATA2 has been reported as an oncogene, GATA2 expression was increased in ZFP90 knockout HCT116 cells, and ZFP90 knockout blocked colorectal carcinogenesis, we chose BMP4 as the biological candidate target of ZFP90 for validation." (PMID 31641208, 2020).
inflammation (2 papers, 2022 to 2024). Aberrant reaction of the microcirculation characterized by movement of fluid and leukocytes from the blood into extravascular tissues. "Current research shows that the combination of ellagic acid-hydroxyapatite combination is able to reduce the main proinflammatory cytokine of bone inflammation, TNF-α so that it can increase bone growth factors, BMP-4 and OPN, through IL-10." (PMID 36561943, 2022).
musculoskeletal disorders (2 papers, 2020 to 2025). "We revealed associations between the serum levels of BMP-4 at the admission and with a history of musculoskeletal disorders (r = 0.6, p < 0.05), with the patient’s age (r = −0.6, p < 0.05)." (PMID 32992577, 2020). "This likely explains the presence of correlations between the values of BMP-4 with the history of musculoskeletal disorders pathology and with patients’ age in our sample." (PMID 32992577, 2020).
neurodegenerative disease (2 papers, 2013 to 2024). A disorder of the central nervous system characterized by gradual and progressive loss of neural tissue and neurologic function. "The PPI network analysis showed that Ngfr directly interacts with genes associated with neurodegenerative diseases, such as Bmp4, Ngf, and Angpt2." (PMID 38396669, 2024). "The protective effects of BMP4 seen during both glutamate exposure and recovery periods in this study may provide for a better intervention for treating motor neuron and other neurodegenerative diseases in the future." (PMID 23472198, 2013).
cardiac disease (1 paper, 2022). "In addition, we found several upregulated genes that are implicated in cardiac disease, including bone morphogenetic protein 4 (Bmp4) (LogFC 0.728), α-actin (Acta1) (LogFC 3.335), and myosin heavy chain β (Myh7) (LogFC 1.954)." (PMID 35603785, 2022).
connective tissue disorder (1 paper, 2025). A disease involving the connective tissue. "Notably, of the 29 children with nFTS with dysmorphic features resembling connective tissue disorders, 7 had VUSs of genes known to be related to connective tissue (BMP4, MATN3, COL2A1, COL11A1, COL1A1, COL1A2, and COL6A3)." (PMID 40524006, 2025).
myopathy (1 paper, 2020). A disease of the muscle in which the muscle fibers do not function properly. "Furthermore, Bmp4 was increased in patient myoblasts of the LMNA myopathy, while Bmp4 downregulation or Smad6 overexpression in mutant myoblast cultures promoted myogenic differentiation in vitro." (PMID 32053985, 2020).
skeletal diseases (1 paper, 2025). "Polymorphisms in BMP2 and BMP4 genes, such as rs235756 (BMP2) and rs17563 (BMP4), have been associated with cardiovascular and skeletal diseases." (PMID 39997941, 2025).
BMP4 also shares sentences with these, for which no sentence is quoted: multiple myeloma (4 papers); primary open angle glaucoma (4); ischemia (3); lung squamous cell carcinoma (3); non-small cell lung carcinoma (3); pulmonary hypertension (3); ameloblastoma (2); Anxiety (2); cardiomyopathy (2); cataract (2); Chorioretinal coloboma (2); essential hypertension (2); fibrodysplasia ossificans progressiva (2); fibrosarcoma (2); mammary adenocarcinoma (2); mesothelioma (2); nonalcoholic steatohepatitis (2); Parkinson disease (2); premature ovarian failure (2); retinal degeneration (2); Stroke (2); adrenocortical cancer (1); age (1); aggressive periodontitis (1); amyotrophic lateral sclerosis (1); anorectal malformation (1); Arrhythmia (1); astrocytomas (1); atrioventricular septal defects (1); Atrophy (1).
A further 113 diseases each share a sentence with BMP4 in 1 paper.